CCL4 (C-C motif chemokine ligand 4)
Diseases named in the same sentence as CCL4 in open-access papers (continued):
Sharing a sentence is not in itself a finding about the gene and the disease.
infection (continued). "In addition, aged ferrets showed high expression of chemokines (CCL4 and CXCL10) and inflammatory cytokines (IFNB1, IL1B, IL6, and IL7) in the early phase of infection." (PMID 35013229, 2022). "Similarly, while SARS-CoV-2 infection alone induced a minimal expression of the inflammatory chemokines, the IAV single-infection group induced significantly high levels of CCL3, CCL4, CCL5, and CXCL9." (PMID 35107382, 2022). "Venn diagram analysis showed that among the common DGEs in the 3 h and 12 h infection groups compared with the control group, 11 differential genes were enriched in the NF-κB signaling pathway, including CXCL8, IL-1β, CCL4, IκBα, TNF, NF-κB, CFLAR, PTGS2, TRAF1, PLAU, and IL-1β2." (PMID 35215890, 2022). "It is, therefore, conceivable that CCL-4, CCL-5, CXCL-10 and IL-8 would initiate and maintain the inflammatory response in the acute phase of infection and the increased release of CCL-2 during the convalescent phase would regulate the immune response in order to reduce immune pathologies." (PMID 35543881, 2022). "The mRNA expression of various inflammatory cytokines (Il-6, Tnf-α, Ifn-γ, and Ifn-β) and chemokines (Ccl2, Ccl4, Ccl12, Cxcl1, and Cxcl10), but not Il-1β, was elevated in the lungs at 2 dpi, in the early stage of infection." (PMID 34463644, 2021). "We found that the expression of CX3C subfamily (CX3CL1) and the C subfamily member (XCL1) was only highly increased in the H9N2-infected mice compared to the mock control, but the expression of CCL4, CXCL1, and CXCL2 was significantly increased in both single infection groups." (PMID 33968006, 2021). "RT7806 cells, although not the highest CCL4 expressers on infection, did demonstrate a sustained response over time versus other donors." (PMID 33652921, 2021). "In addition, patients with acute toxoplasmosis showed significantly higher plasma levels of CCL4, CXCL9, and CXCL10 than patients in the chronic phase of infection or HDs." (PMID 34607465, 2021). "Since CD8+ T cells may block HIV/SIV spread from cell- to-cell via CCR5-binding chemokines (i.e., MIP-1a/CCL3, MIP-1b/CCL4, and RANTES/CCL5), we also used viruses which were limited to a single cycle of infection." (PMID 32941545, 2020). "PrimePCR array analysis of hNS/PCs showed that the mRNA levels of inflammatory cytokine related genes (IL-1A, TNFα, IL28A, IL29, NF-KB2), chemokines (CSF2, CCL3, CCL4, CXCR3),TLRs (TLR3, TLR8), IL-10, and Casp9 were all reduced in the Smaducin-6 treated group following ZIKV-FSS13025 infection." (PMID 32544190, 2020). "The chemokine genes (CCL3, CCL4 and CCL5) were also upregulated in these memory-like γδ T cells, which is similar to what had previously been reported to be upregulated in γδ T cells during an active infection." (PMID 33154754, 2020). "To identify mechanistic bases for the different numbers of neutrophils at the site of infection, we measured the main chemokine factors for neutrophil attraction, including the CCR1 ligands CCL3, CCL4, and CCL5 and the CXCR2 ligands MIP-2/CXCL-2, KC/CXCL-1, and CXCL5." (PMID 32424099, 2020). "In the lungs, the levels of proinflammatory cytokines, including interleukin-1β (IL-1β) and granulocyte colony-stimulating factor (G-CSF), and of chemokines, including IP10/CXCL10, MIP1-α/CCL3, MIP1-β/CCL4, MIP2/CXCL2, and KC/CXCL1, were increased and remained high after the infection with WT cells." (PMID 30940711, 2019). "We also found that protein levels of IL-6, IL-12p40, IL-12p70, CCL2, CCL3 and CCL4 were not suppressed in response to rosiglitazone treatment during super-infection." (PMID 31159430, 2019). "Regarding the chemokines, diverse studies in humans and mice have indicated that CXCL1, CXCL9, CXCL10, CCL2, CCL3, CCL4, and CCL5 are important in controlling the infection during the acute phase, and the levels of virtually all of them were increased in both BALB/c and C57BL/6 mice." (PMID 29662478, 2018).
infection (continued). "By nanoString and real-time PCR profiling of the host response to the various mutants, we found that infection with the ΔgliP mutant enhanced expression of multiple chemokines, including CXCL2, CCL3, CCL4, and CCL7, which recruit neutrophils and macrophages to sites of inflammation." (PMID 30052103, 2018). "Severe IV infection induces many cytokines; IFNαβ, TNFα, IFNγ, C-X-C motif chemokine (CXCL) 10 (CXCL10), CXCL9, C-C motif ligand (CCL) 2 (CCL2), CCL4, CCL5 and interleukin (IL)−6 (IL-6), IL-2, IL-8, and IL-10 have all be observed to be upregulated during severe IV infection in humans." (PMID 30250466, 2018). "Infection of human neutrophils with IAV treated at 56°C to denature the viral replicase but not HA suggested that infection alone, but not replication, is sufficient to stimulate the release of CXCL8 and CCL4 in human neutrophils." (PMID 28553293, 2017). "Within this group, IFNα, CCL4, CXCL1, and CXCL10 were upregulated following ArmΔGPC priming but prior to infection with Cl13, suggesting that these cytokines were upregulated not only upon Clone 13 infection but also by the priming agent." (PMID 25569216, 2015). "Furthermore, our study also showed decreased expression of the chemokines CCL3, CCL4 and CCL5 in the liver and ileum of CCR5-/- mice along with reduced induction of the transcription factors Foxp3, T-bet and GATA-3 after infection." (PMID 25119429, 2014). "Three months before the discovery of CXCR4 as a co-receptor for HIV, it had been reported that CCL3L1 (MIP-1αP), CCL4 (MIP-1β) and CCL5 (RANTES) could block infection." (PMID 23692808, 2013). "However, levels of mRNAs for some chemokines, including CCL4 and CXCL10, were up-regulated compared to mock-infected cells at this time point following infection." (PMID 23265239, 2013). "Indeed, when similar infectious doses are applied, although infection with virulent Kp52.145 is lethal, the cytokines IL-1β, IL-6, and IL-17 and the chemokines CCL2, CCL3 and CCL4 are produced in similar manner." (PMID 23554169, 2013). "The observed down-regulation of chemokine (CCL4) and chemokine receptors (CCR1, CXCR2, CX3CR1, C5aR) could impair the proper inflammatory response at the site of infection as they play a crucial role in immune cell trafficking." (PMID 23626859, 2013). "CCL-3 and CCL-4 levels were significantly upregulated by in vitro infection with R5 HIV-1 but not X4." (PMID 21767373, 2011). "High expression levels of lymphocyte activation marker (CD38), TLR2, macrophage inflammatory protein (CCL4) and osteopontin (SPP1) at 4 weeks that was sustained until 16 weeks of infection suggested an early and robust inflammation in the lungs in association with progression of the disease." (PMID 22645653, 2011). "In untreated rabbits, most of these genes were progressively induced by Mtb infection from 4 to 8 weeks, and many had reached a plateau (IFN-γ, IL13, IL6, MIF, CCL4, NFκB, APRIL, TLR2, RAB7 and LAMP2) or were even reduced (IL10, CXCR3, GMCSF and PI3K3) by 12 weeks post-infection." (PMID 21949656, 2011). "Strikingly, innate immune genes (whose transcript abundances are typically altered in response to other pathogens or insults including IL-8, CCL4, and IL-1β) showed no or very little change at any time point following infection." (PMID 22331987, 2010). "Similarly, stimulation of M1 macrophages with an NF‐κB activator and subsequent infection with Omicron BA.5 resulted in increased production of the inflammatory factors CCL3 and CCL4; nevertheless, intervention with IL‐37 significantly attenuated the expression of these chemokines." (PMID 40452816, 2025). "Additionally, CD8+CTLs release CCL3 (macrophage inflammatory protein-1α or MIP-α) and CCL4 (MIP-1β), which may further optimize local Ag presentation by increasing APC infiltration at the infection/inflammatory site." (PMID 41009359, 2025).
infection (continued). "In addition, higher levels of CCL2/MCP-1, IL-6, and Macrophage inflammatory protein-1 (CCL4/MIP-1β) and decreased levels of Regulated upon Activation, Normal T-cell Expressed and Secreted (CCL5/RANTES) are observed in the chronic phase of infection and arthritic cases." (PMID 38543735, 2024). "In particular, the transcription level of some cytokines in the splenic lymphocytes, including IL-1β, IL-6, IL-8L1, and CCL4, which are related to B cell activation and antigenic signal transduction to T cells, were significantly upregulated by MDV/CVI988 infection compared with MDV/RB1B infection." (PMID 36680047, 2022). "As infection progressed in the vehicle controls, increased amounts of IL-6 and TNF-α, along with chemokines responsible for monocyte and neutrophil recruitment (CCL2, MIP-2a, and CCL4), were detected in the serum, and this pattern of inflammation was mirrored in the lungs." (PMID 34835277, 2021). "Instead, we observed chemokines as particularly affected by the presence of the parasite, since IL-8, CCL3, CCL4 and CCL5 were significantly reduced in concentration in Ss+ subjects compared to CTRL, suggesting that immune cell recruitment to the infection site might be dampened in these patients." (PMID 33059754, 2020). "Finally, the neutrophil recruitment after rHMPV-ΔG infection could have also been altered by the reduced expression of CCL3 and CCL4, which are neutrophil-active chemokines." (PMID 29065494, 2017). "Infection with both low and high virulence isolates resulted in down-regulation of mRNA levels for chemokines CCL2, CCL3L, CXCL2 and chemokine receptors CCR1, CCR5, CXCR3, CXCR4 and up-regulation in expression of mRNAs for CCL4, CXCL10 and chemokine receptor CCR7." (PMID 23265239, 2013). "Acute HIV infection also induces production of chemokines (CCL2, CCL3, CCL4, and CCL5), which may recruit uninfected monocytes/macrophages and/or CD4+ T lymphocytes to the sites of virus replication, thus promoting the spread of infection and/or the establishment of virus reservoirs." (PMID 40507836, 2025). "In our study, BVDV-2 infected goat PBMCs showed increased transcription of CCL3, CCL4, CCL5, CCL20, CXCL10 and decrease of CCL2, suggesting that such chemokines may contribute to the recruitment and regulation of macrophages or other inflammatory cells to the infected sites after infection." (PMID 31226933, 2019). "Following CB4 challenge, TLR3KO mice produced similar levels of CCL2 and CXCL9 while levels of CCL3 and CCL4 were slightly reduced but were not significantly different from either WT NOD controls or MyD88KO mice suggesting that these chemokines are not critical for survival following infection." (PMID 19122812, 2009). "By contrast, the Ifih1−/−Sting1gt/gt AECII failed to induce Ifnb1, Ccl4, and Ccl5 gene expression and to produce IFN-β, CCL4 and CCL5 upon VACV∆C7L infection." (PMID 35351885, 2022). "Infection of female mice with M. circinelloides but not males resulted in increased levels of CCL2, CCL3 and CCL4." (PMID 33919611, 2021). "CCR5 and CCL4 genes are overexpressed in PRRSV-infected swine compared to in non-infected swine, 7 days post-infection (dpi)." (PMID 34438623, 2021). "When the infection was mostly cleared in WT mice (day 9), we observed a decrease in most chemokines, but not in IL-1α and IL-1β, CCL7, and CCL4." (PMID 30102746, 2018). "When mice were depleted of neutrophils at 8 weeks post-infection and evaluated at 12 weeks post-infection, they showed significant decrease in levels of CCL3 (MIP-1α), CCL4 (MIP-1β), CXCL1 (KC), LIF, G-CSF and M-CSF (Data not shown)." (PMID 27690127, 2016). "L. major induced only a small increase in CCL4 and CCL5 mRNA at the site of infection, while infection did not induce CCL20 mRNA (data not shown)." (PMID 20140197, 2010).
infection (continued). "Interestingly, we found differences in the expression of several immune-barrier molecules (filaggrin, MIP-1α/CCL3, MIP-1β/CCL4 and MCP-1) in NPA supernatants of virus-negative controls compared to negative pre-infection samples of RVI neonates." (PMID 36482106, 2022). "All other markers (CCL4, IL-1Ra, TNF, S100A12, ferritin, C1q, CRP, and ApoA1) yielded no or hardly any detectable signals or failed to discriminate before and after infection (ApoA1, C1q)." (PMID 34943175, 2021). "We found that the majority of CD11b+ LyChi Ly6G- CD64+ inflammatory monocytes present in the ear of VACV-infected mice at 5 days post-infection were CCR5+, the receptor for CCL4, rather than CCR2+, or positive for the receptors for CXCL13 (CXCR5) or CXCL9 and CXCL10 (CXCR3)." (PMID 31603920, 2019). "Furthermore, of the cytokines whose secretion was elevated by 1,25D treatment after infection (CCL3, CCL4, CCL8, IL-8, and TNF-α), treatment did not induce their secretion from uninfected cells." (PMID 23762029, 2013). "The addition of IFNγ after infection not only resulted in a dramatic increase of the translation of the before mentioned genes but also in the translation of IFNß1, IL12ß, MIP1 and CCL3, CCL4, NOS2 and SOD2, and FAS but, nevertheless, did not prevent multiplication of the bacteria." (PMID 32462327, 2020). "Since we had observed production of higher levels of CCL3 and not the CCL4 and CCL5 chemokines by LdCen-/ -infected neutrophils, we therefore assessed whether chemo-attractive activity of CCL3 itself is necessary and sufficient to explain the elevated DC migration observed in LdCen-/- infection." (PMID 35192633, 2022).
cancer (138 papers, 2007 to 2026). A tumor composed of atypical neoplastic, often pleomorphic cells that invade other tissues. "Basic characteristics of included studies on the relationship between CCL4 rs10491121 polymorphism and cancer susceptibility." (PMID 37593100, 2023). "Although numerous case-control studies have explored the association between CC cytokine ligand-4 (CCL4) expression and cancer susceptibility, their results have been conflicting." (PMID 37593100, 2023). "Basic characteristics of included studies on the relationship between CCL4 rs1634507 polymorphism and cancer susceptibility." (PMID 37593100, 2023). "CCL3 and CCL4 cause increased expression of VEGF in a cancer cell, a growth factor causing angiogenesis." (PMID 33076281, 2020). "Furthermore, cytokines Ccl2, Ccl4, Ccl7, Ccl22, and Il21r, which associated with an M2-like, pro-cancer macrophage phenotype, were found to be consistently downregulated at both days 5 and 10 post-challenge." (PMID 37066426, 2024). "This study aimed to determine the still-unknown connection of CCL4 rs10491121 and rs163450 polymorphisms with cancer susceptibility." (PMID 37593100, 2023). "Notably, mutations at the two classical mutation sites of the CCL4 gene, namely rs1634507 and rs10491121, are reportedly closely related to many cancers." (PMID 37593100, 2023). "Publication bias analysis of the rs10491121 gene polymorphism of CCL4 and cancer susceptibility." (PMID 37593100, 2023). "Subgroup analysis of CCL4 rs1634507 polymorphism and cancer susceptibility." (PMID 37593100, 2023). "Publication bias analysis of the rs1634507 gene polymorphism of CCL4 and cancer susceptibility." (PMID 37593100, 2023). "Others suggest that CCL4/5 chemokines may serve as attractive diagnostic and therapeutic targets in detecting and antagonizing life-threatening cardiac irAE in cancer patients treated with ICI44." (PMID 37736764, 2023). "Subgroup analysis of CCL4 rs10491121 polymorphism and cancer susceptibility." (PMID 37593100, 2023). "Consequently, although the study does offer significant insights into the association between CCL4 SNPs and cancer susceptibility, caution should be exercised when interpreting the findings." (PMID 37593100, 2023). "Similar to our data, CCL4 expression is linked with poor prognosis in cancer." (PMID 32961854, 2020). "Therefore, it is reasonable to speculate that polymorphisms that cause changes in expression level and activity contribute of CCL4 to cancer susceptibility in patients." (PMID 37593100, 2023). "These variables may have influenced the relationship between cancer susceptibility and CCL4 SNPs." (PMID 37593100, 2023). "In this way, increased CCL4 expression may lower the risk of cancer and provide a better prognosis." (PMID 37593100, 2023). "In the tumor microenvironment, CCL3 and CCL4 help to establish a favorable niche for cancer cell dissemination." (PMID 40076892, 2025). "In spite of the fact that its contribution to cancer development was first mentioned in 1964, like all other chemokines, the data linking CCL4 and metastasis only emerged in the last 2–3 decades." (PMID 40076892, 2025). "Conversely, our findings regarding the protective effects of CD40 and CCL4 (OR = 0.857, p = 0.015; OR = 0.896, p = 0.049) highlight the complexity of immune‐inflammatory interactions in cancer." (PMID 40682474, 2025). "Consistent with this phenotype, PT-associated macrophages expressed inflammatory cytokines (TNF, IL6) and pro-tumorigenic factors (CCL2, CCL3, CCL4, CXCL16) linked to cancer progression and invasiveness." (PMID 41346635, 2025). "The chemokines CCL2 and CCL4 recruit leukocytes to the site of injury or cancer, although IFNγ and its inducible IP-10 activate lymphocytes against infections or tumors." (PMID 40145019, 2025).